Y_RNA (Y RNA )
Gene: Miscellaneous RNA gene on chromosome 7 (152,402,780 to 152,402,893, forward strand). Ensembl gene ENSG00000253088.
Homologues: Orthologues: chimpanzee Y_RNA (99% identical). Paralogues in human: Y_RNA (78% identical), RNY1 (77% identical), Y_RNA (77% identical), Y_RNA (76% identical), Y_RNA (75% identical), RNY1P11 (75% identical), RNY1P8 (75% identical), Y_RNA (74% identical), RNY1P5 (73% identical), Y_RNA (73% identical), Y_RNA (72% identical), RNY1P16 (71% identical), and 89 more.